FBXL18 (F-box and leucine rich repeat protein 18)
Description:
Substrate-recognition component of the SCF (SKP1-CUL1-F-box protein)-type E3 ubiquitin ligase complex.
Synonyms: FBL18; FLJ11467
Tractability: PROTAC: ubiquitination databases record sites on it; its protein half-life has been measured.
Gene: Protein-coding gene on chromosome 7 (5,431,335 to 5,513,809, reverse strand). Ensembl gene ENSG00000155034.
Subcellular location (Human Protein Atlas): Nucleoplasm; Cytosol
Pathways (Reactome):
Cell Cycle: FBXL7 down-regulates AURKA during mitotic entry and in early mitosis
Immune System: Antigen processing: Ubiquitination & Proteasome degradation
Metabolism of proteins: Neddylation
Gene Ontology:
Biological process: regulation of apoptotic process; SCF-dependent proteasomal ubiquitin-dependent protein catabolic process
Cellular component: cytosol
Genetic constraint (gnomAD): Loss-of-function variants: 36 observed, 41.42 expected, observed/expected ratio (o/e) 0.87, 90% interval 0.67 to 1.15. The synonymous counts are far from expectation, so gnomAD's model fits this gene poorly and the ratio says little. Missense variants: 977 observed, 995.42 expected, observed/expected ratio (o/e) 0.98, 90% interval 0.93 to 1.03. Synonymous variants: 557 observed, 463.04 expected, observed/expected ratio (o/e) 1.2, 90% interval 1.12 to 1.29.
Homologues: Orthologues: chimpanzee FBXL18 (99% identical), dog FBXL18 (92% identical), rat Fbxl18 (92% identical), mouse Fbxl18 (91% identical), pig FBXL18 (91% identical), rat Fbxl18l1 (91% identical), rabbit FBXL18 (90% identical), guinea pig FBXL18 (90% identical), tropical clawed frog fbxl18 (64% identical), zebrafish fbxl18 (51% identical), Caenorhabditis elegans fbxl-1 (12% identical), Drosophila melanogaster CG9003 (12% identical), and 24 more. Paralogues in human: FBXL20 (13% identical), FBXL2 (13% identical), FBXL13 (12% identical), FBXL6 (12% identical), FBXL7 (12% identical), FBXL4 (11% identical), SKP2 (11% identical), FBXL3 (11% identical), FBXL16 (10% identical), FBXL15 (9% identical), FBXL19 (9% identical), FBXL5 (9% identical), and 3 more.
Diseases named in the same sentence as FBXL18 in open-access papers:
FBXL18 is named in the same sentence as 10 diseases in open-access papers, as found by Europe PMC text mining. Sharing a sentence is not in itself a finding about the gene and the disease. The quoted sentences say what the papers report.
glioma (5 papers, 2017 to 2024). A benign or malignant brain and spinal cord tumor that arises from glial cells (astrocytes, oligodendrocytes, ependymal cells). "F-Box and FBXL18 can activate PI3K-Akt signaling in glioma cells by promoting the K63-linked ubiquitination of Akt." (PMID 38303029, 2024). "FBXL18 has been reported to play an oncogenic role in glioma through promoting K63-linked ubiquitination of Akt." (PMID 32576198, 2020). "Moreover, the subunit of SCF complex F-Box and Leucine Rich Repeat Protein 18 (FBXL18) promotes the glioma progression by inducing the K63-linked ubiquitination of Akt." (PMID 36769122, 2023). "The F-box protein FBXL18 promotes glioma progression by promoting K63-linked ubiquitination of Akt." (PMID 28744466, 2017). "FBXL18 was reported to be an oncogene in glioma and cervical cancer." (PMID 37378633, 2023).
bladder cancer (1 paper, 2022). "FBXL18 played a role in the migration of bladder cancer cell line." (PMID 35456446, 2022).
diabetes (1 paper, 2020). "For instance, target genes (FLAD1, SLFNL1, GNS, FBXL18, CYP2B7P) are commonly upregulated genes in metabolic-induced HCC and are associated with risk factors, such as diabetes, obesity, and other metabolic syndromes." (PMID 32228601, 2020).
tumor (3 papers, 2020 to 2023). "FBXL18 was positively associated with TNM stage, histological grade, tumor size, vascular thrombosis, and metastasis in HCC patients, indicating that FBXL18 expression is positively correlated with poor prognosis in HCC patients." (PMID 37378633, 2023). "In this study, we found that FBXL18 protein expression was increased in tumor tissues compared with adjacent normal liver tissues." (PMID 37378633, 2023). "We found that the mRNA levels of some F-box proteins were significantly increased in HCC samples when compared with non-tumor tissues, including FBXL18, FBXL16 and FBXL6." (PMID 32576198, 2020). "Mice with high FBXL18 expression (OE-FBXL18 mice; n = 14) developed more liver tumors, larger tumor sizes, and increased liver and body ratios compared with WT mice (n = 16) up until 24 weeks, demonstrating that FBXL18 overexpression drives hepatocarcinogenesis in mice." (PMID 37378633, 2023). "In addition to its role in tumorigenesis, a tumor suppressor role of FBXL18 has been indicated in other cancers." (PMID 37378633, 2023).
cancer (2 papers, 2023 to 2024). A tumor composed of atypical neoplastic, often pleomorphic cells that invade other tissues. "F-box and leucine-rich repeat protein 18 (FBXL18) is an E3 ubiquitin ligase that is reported to be involved in the tumorigenesis of various types of cancer." (PMID 37378633, 2023). "Compared to other members of the FBXL subgroup, the functions and mechanisms of FBXL18 in cancers remain incompletely understood." (PMID 37378633, 2023).
neurodegenerative disease (1 paper, 2021). A disorder of the central nervous system characterized by gradual and progressive loss of neural tissue and neurologic function. "One of the functions of the SCF complex is to eliminate misfolded proteins, and various components of the complex (SKP1, Cullin1, FBXL5, FBXO7, FBXL18, Parkin) have been associated with neurodegenerative diseases." (PMID 34709416, 2021).
FBXL18 also shares sentences with these, for which no sentence is quoted: cervical cancer (1 paper); iridocyclitis (1); metabolic syndrome (1); Obesity (1).